H4C15 (H4 clustered histone 15)
Description:
Core component of nucleosome. Nucleosomes wrap and compact DNA into chromatin, limiting DNA accessibility to the cellular machineries which require DNA as a template. Histones thereby play a central role in transcription regulation, DNA repair, DNA replication and chromosomal stability. DNA accessibility is regulated via a complex set of post-translational modifications of histones, also called histone code, and nucleosome remodeling.
Synonyms: H4/O; HIST2H4B
Target class: Other nuclear protein
Gene: Protein-coding gene on chromosome 1 (149,854,045 to 149,861,159, reverse strand). Ensembl gene ENSG00000270276.
Subcellular location: Nucleus; Chromosome
Pathways (Reactome):
Gene expression (Transcription): B-WICH complex positively regulates rRNA expression; DNA methylation; ERCC6 (CSB) and EHMT2 (G9a) positively regulate rRNA expression; MLL4 and MLL3 complexes regulate expression of PPARG target genes in adipogenesis and hepatic steatosis; NoRC negatively regulates rRNA expression; PRC2 methylates histones and DNA; RNA Polymerase I Promoter Escape; RNA Polymerase I Promoter Opening; RUNX1 regulates genes involved in megakaryocyte differentiation and platelet function; RUNX1 regulates transcription of genes involved in differentiation of HSCs; Regulation of endogenous retroelements by KRAB-ZFP proteins; Regulation of endogenous retroelements by Piwi-interacting RNAs (piRNAs); Regulation of endogenous retroelements by the Human Silencing Hub (HUSH) complex; SIRT1 negatively regulates rRNA expression; Transcriptional regulation by small RNAs
Chromatin organization: CHD1 and CHD2 subfamily; CHD6, CHD7, CHD8, CHD9 subfamily; ChAHP complex assembly; HATs acetylate histones; HDACs deacetylate histones; HDMs demethylate histones; Interaction of NuRD complexes with transcription factors; NuRD complex assembly; PKMTs methylate histone lysines; RMTs methylate histone arginines
DNA Repair: Cleavage of the damaged purine; Cleavage of the damaged pyrimidine; Nonhomologous End-Joining (NHEJ); Processing of DNA double-strand break ends; Recognition and association of DNA glycosylase with site containing an affected purine; Recognition and association of DNA glycosylase with site containing an affected pyrimidine; Recruitment and ATM-mediated phosphorylation of repair and signaling proteins at DNA double strand breaks
Cell Cycle: Condensation of Prophase Chromosomes; Deposition of new CENPA-containing nucleosomes at the centromere; G2/M DNA damage checkpoint; Inhibition of DNA recombination at telomere; Packaging Of Telomere Ends
Developmental Biology: Activation of anterior HOX genes in hindbrain development during early embryogenesis; Chromatin modifications during the maternal to zygotic transition (MZT); Replacement of protamines by nucleosomes in the male pronucleus
and 20 more pathways
Gene Ontology:
Molecular function: protein binding; RNA binding; structural constituent of chromatin; DNA binding; protein heterodimerization activity
Biological process: negative regulation of megakaryocyte differentiation; nucleosome assembly; chromatin organization; protein localization to CENP-A containing chromatin; telomere organization
Cellular component: CENP-A containing nucleosome; chromosome, telomeric region; extracellular exosome; membrane; nucleoplasm; nucleosome; nucleus; protein-containing complex; extracellular region; chromosome
Homologues: Orthologues: guinea pig H4C15 (100% identical), macaque H4C12 (100% identical), rat Hist1h4m (100% identical), tropical clawed frog h4c3 (100% identical), zebrafish si:dkey-108k21.28 (100% identical). Paralogues in human: H4C1 (100% identical), H4C11 (100% identical), H4C12 (100% identical), H4C13 (100% identical), H4C14 (100% identical), H4C16 (100% identical), H4C2 (100% identical), H4C3 (100% identical), H4C4 (100% identical), H4C5 (100% identical), H4C6 (100% identical), H4C8 (100% identical), and 2 more.
Diseases named in the same sentence as H4C15 in open-access papers:
H4C15 is named in the same sentence as 4 diseases in open-access papers, as found by Europe PMC text mining. Sharing a sentence is not in itself a finding about the gene and the disease. The quoted sentences say what the papers report.
pneumonia (1 paper, 2022). An acute, acute and chronic, or chronic inflammation focally or diffusely affecting the lung parenchyma, caused by an infection in one or both of the lungs (by bacteria, viruses, fungi, or mycoplasma.). "In conclusion, we discover that NETosis is critical in SCAP and highlight H4C15, H3-5, DNASE1, and PRKCB as promising therapeutic targets for severe pneumonia." (PMID 36466920, 2022).
H4C15 also shares sentences with these, for which no sentence is quoted: Alcoholism (1 paper); infection (1); systemic lupus erythematosus (1).